TNFRSF1A (TNF receptor superfamily member 1A)
Diseases named in the same sentence as TNFRSF1A in open-access papers (continued):
Sharing a sentence is not in itself a finding about the gene and the disease.
lung carcinoma (24 papers, 2012 to 2025). "In summary, our study showed that MAD2L2 rs746218 was significantly associated with platinum-based chemotherapy, and PFS and TNFRSF1A rs4149570 was significantly associated with OS time in patients with lung cancer treated with platinum-based chemotherapy." (PMID 35899106, 2022). "Polymorphisms of MAD2L2 rs746218 and TNFRSF1A rs4149570 polymorphisms may be biomarkers for predicting prognosis in patients with lung cancer treated with platinum-based chemotherapy." (PMID 35899106, 2022). "The results indicated that the genes FADD, TNFRSF1A, CASP9, MLKL, and CASP4 were the risk factor for lung cancer patients (p < 0.05)." (PMID 36874021, 2023). "TNF inhibition via TNFRSF1A silencing, etanercept, or thalidomide increases sensitivity of lung cancer cells to EGFR-TKIs, whereas TNF overexpression attenuates apoptosis induction by EGFR-TKIs." (PMID 35372081, 2022). "Our results showed that MAD2L2 rs746218 and TNFRSF1A rs4149570 may be biomarkers for predicting the prognosis of patients with lung cancer in response to platinum-based chemotherapy." (PMID 35899106, 2022). "In this study, we also investigated the correlations between 35 polymorphisms in 9 DNA repair genes (XRCC3, BRCA2/ZAR1L, XPC, RAD52, MAD2L2, NFKB1, NFKBIA, TNFRSF1A, and FASN) with platinum-based chemotherapy prognosis in 399 patients with lung cancer." (PMID 35899106, 2022). "Expression analysis reveals that hypoxia induced lung cancer related biomarkers, HIF and its modulating proteins (TGM2, CSNK1A1, CTNNA1, NAMPT/Visfatin, TNFRSF1A, ETS1, SRC-1, FN1, APLP2, DMBT1/SAG, AIB1 and AZIN1) are significantly down regulated." (PMID 23122428, 2012). "The HIF, TGM2, CSNK1A1, CSNK2A1, CTNNA1, NAMPT)/Visfatin, TNFRSF1A, ETS1 and SRC-1 were down-regulated and proposed as the biomarkers for lung cancer." (PMID 23122428, 2012).
Insulin resistance (21 papers, 2012 to 2025). Increased resistance towards insulin, that is, diminished effectiveness of insulin in reducing blood glucose levels. "The heightened TNFRSF1A expression correlated closely with insulin resistance, inflammation, and hepatic lipid deposition." (PMID 40918148, 2025). "TNFRSF1A encodes TNFR1, a mediator of pro-inflammatory responses and apoptosis pivotal in pathogenesis of insulin resistance and liver inflammation." (PMID 40918148, 2025).
depression (20 papers, 2008 to 2026). "TNFRSF1A gene encodes tumor necrosis factor receptor 1 (TNFRSF1A) and has been implicated in poststroke depression, where cerebellar fastigial nucleus stimulation reduces its expression to attenuate inflammation and disease severity." (PMID 41235394, 2025). "As previous studies, TNFRSF1A could be mediated by microR-29c, thereby reducing poststroke depression." (PMID 32964047, 2020).
viral infection (20 papers, 2009 to 2025). "We confirmed variants with putative driver role of MAP10, MPZL1, RPS6KA1, SETD1B, TAOK2, TMEM127, and TNFRSF1A genes, and of genes linked to viral infections (DDX3X and RSF1) and DNA repair (PAXIP1)." (PMID 32321919, 2020).
experimental autoimmune encephalomyelitis (19 papers, 2011 to 2025). An autoimmune demyelinating disease of the central nervous system that is produced experimentally in animals by the injection of homogenized brain or spinal cord in Freund's adjuvant. "Experiments using knockout mice have shown, that mice with no functional p55 (TNFR1/Tnfrsf1a/CD120a) receptor were resistant to experimental autoimmune encephalomyelitis (EAE), the rodent model of MS." (PMID 21552549, 2011).
dermatitis (18 papers, 2014 to 2025). An inflammatory process affecting the skin. "Double deficient Sharpincpdm/cpdm;Tnfrsf1a−/− mice did not develop skin inflammation, demonstrating that TNF-induced TNFR1 signaling is essential for the pathogenesis of inflammatory skin lesions in Sharpincpdm/cpdm mice." (PMID 25443631, 2014). "TNFR1 activity is directly required for the skin inflammation in cpdm mice as SHARPIN-null animals that were also null for Tnfrsf1a did not develop cutaneous inflammation." (PMID 37569318, 2023).
glaucoma (18 papers, 2009 to 2024). Increased pressure in the eyeball due to obstruction of the outflow of aqueous humor. "The finding that overall TNFR1 immunoreactivity remains relatively unchanged contrasts with our data suggesting elevated mRNA levels of the TNFR1 gene (TNFRSF1A) in glaucoma." (PMID 21042562, 2010). "Our results indicated upregulation of TNF-α receptor TNFRSF1A and furthermore it has been reported that the concentration of TNF-α in the aqueous humor of glaucoma patients is elevated so it is conceivable that this pathway was activated in glaucomatous TF cells." (PMID 38990974, 2024).
heart failure (18 papers, 2013 to 2025). Inability of the heart to pump blood at an adequate rate to meet tissue metabolic requirements. "Transcript levels of several established biomarkers, including Spp1, Sfrp1, Sfrp2, Tnc, Vim, Mmp9, and Tnfrsf1a, and several inflammatory markers that are known to be activated in heart failure, such as Cd44, Cd83, Ccl7, Irf7, and Nr4a2, were upregulated in the Myh6-McmTamDspfl/fl cardiomyocytes." (PMID 40608429, 2025).
Crohn disease (17 papers, 2012 to 2024). A gastrointestinal disorder characterized by chronic inflammation involving all layers of the intestinal wall, noncaseating granulomas affecting the intestinal wall and regional lymph nodes, and transmural fibrosis. "In Crohn’s disease, we reported that SNPs in TNFα and receptors (TNFRSF1A/TNFRSF1B) benefited intracellular MAP-survival, increased infection, and elevated inflammatory response mimicking the poor response to anti-TNFα treatment in some patients." (PMID 31817071, 2019).
liver disease (17 papers, 2003 to 2025). "Combined with the higher association of TNFRSF1A with liver-related diseases or injury than infections, it seemed that TNFRSF1A may be specific in liver disease." (PMID 36299685, 2022). "Hepatocyte death is a central event during liver disease progression, in which immune cells play key roles by activating members of the Tumor Necrosis Factor Receptor Superfamily (TNFRSF), including TNFR1 (TNFRSF1A), Fas (TNFRSF6) and TRAIL-R2 (TNFRSF10B)." (PMID 28835677, 2017).
lupus (17 papers, 2012 to 2025). "TNFRSF1A (TNFR1) expression was significantly higher in group 2 lupus participants compared with group 1, and TNFRSF1B (TNFR2) followed a similar insignificant trend." (PMID 39688922, 2024).
liver fibrosis (16 papers, 2013 to 2025). "In cattle, liver fibrosis has been proposed as a downstream effect of upregulated TNF and IL1B, which would activate the genes that were also upregulated in the bovine study, i.e., IL6, PLAU, SERPINE1, TNFRSF1A, SOCS1, and CTSB." (PMID 34616397, 2021).
ischemic stroke (15 papers, 2014 to 2025). A stroke disorder caused by obstruction of blood flow to the brain, due to thrombotic (local blood clot formation) or embolic (due to a blood clot or other material traveling from another site) event. "TNFRSF1A acts as a key PANoptosis-related biomarker and suggests microglial subclusters as therapeutic targets in ischemic stroke." (PMID 41235394, 2025). "Future investigations with larger cohorts, additional time points, and mechanistic studies in vitro and in vivo are warranted to validate these results and to explore the therapeutic potential of TNFRSF1A in ischemic stroke." (PMID 41235394, 2025). "Interestingly, APAF1 and IRAK3 expression correlated negatively with NK cell abundance in both acute myocardial infarction and ischemic stroke, whereas ATM, CAPN1, IL1B, IL1R1, PRKACA, PRKACB, and TNFRSF1A correlated negatively with NK cell abundance in acute myocardial infarction." (PMID 35432334, 2022). "Interestingly, in acute MI and ischemic stroke, the expression of APAF1 and IRAK3 was negatively correlated with the abundance of NK cells, while the expression of ATM, CAPN1, IL1B, IL1R1, PRKACA, PRKACB and TNFRSF1A was positively correlated with the abundance of NK cells in MI." (PMID 38526027, 2024).
schizophrenia (14 papers, 2015 to 2026). A major psychotic disorder characterized by abnormalities in the perception or expression of reality. "We found multiple TNFSF receptor transcripts increased in high-inflammation schizophrenia cases compared with low-inflammation controls, including TNFRSF1A (log2 fold change [FC] = 0.91, adjusted p [p adj.] = 1.93 × 10−10, +87.44% increase), TNFRSF10A (log2FC = 0.56, p adj." (PMID 41567988, 2026). "TNFRSF1A is downregulated in elderly schizophrenia subjects, which may be related to cognitive decline." (PMID 37383091, 2023).
glioblastoma (13 papers, 2014 to 2026). The most malignant astrocytic tumor (WHO grade IV). "To detect the expression levels of C1R, CCL2, and TNFRSF1A in glioblastoma, we analyzed the mRNA levels of GBM patients and glioblastoma cells." (PMID 35726234, 2022). "The results suggested that the expression of C1R, CCL2, and TNFRSF1A might promote the development of glioblastoma." (PMID 35726234, 2022). "The results indicated that the expression of C1R, CCL2, and TNFRSF1A might promote the development of glioblastoma and might be used as molecular biomarkers of prognosis and immune infiltration in GBM patients in the future." (PMID 35726234, 2022). "Moreover, the mRNA expression levels of C1R, CCL2, and TNFRSF1A in glioblastoma cells or in GBM patients were found to be strongly upregulated, and the mRNA expression levels of these three genes were positively associated with each other." (PMID 35726234, 2022).
endotoxemia (12 papers, 2013 to 2024). "As for the receptors, Tnfrsf1a (Tnfr1) was expressed most prominently in microglia and at a lower level in astrocytes, which increased during endotoxemia to a level approximating that of microglia." (PMID 27097852, 2016).
gastric cancer (12 papers, 2012 to 2025). A primary or metastatic malignant neoplasm involving the stomach. "In conclusion, CTHRC1 expression may induce tumor associated macrophage infiltration though GRN/TNFRSF1A and AnxA1/FPR1 pathways and also tumor angiogenesis in gastric cancer." (PMID 35928443, 2022). "In addition, CTHRC1 expression may induce tumor associated macrophage infiltration though GRN/TNFRSF1A and AnxA1/FPR1 pathways and also tumor angiogenesis in gastric cancer." (PMID 35928443, 2022).
Nephropathy (12 papers, 2018 to 2025). A nonspecific term referring to disease or damage of the kidneys. "Recent studies indicate that serum and urine levels of HMGB1 are significantly elevated in DKD patients compared to those with T2DM without nephropathy and are closely associated with TNF receptor superfamily member-1A (TNFR-1)." (PMID 40092979, 2025).
familial Mediterranean fever (11 papers, 2016 to 2023). Familial Mediterranean fever (FMF) is an autoinflammatory disorder characterized by recurrent short episodes of fever and serositis resulting in pain in the abdomen, chest, joints and muscles. "Examples are MEFV/pyrin in familial Mediterranean fever (FMF), TNFRSF1A/TNF receptor type 1 in TNF receptor-associated periodic syndrome (TRAPS), and nucleotide-binding domain, leucine-rich-containing family, pyrin domain-containing 3 (NLRP3) in cryopyrin-associated periodic syndromes (CAPS)." (PMID 28421072, 2017).
ankylosing spondylitis (10 papers, 2014 to 2025). An autoimmune chronic inflammatory disorder characterized by inflammation in the vertebral joints of the spine and sacroiliac joints. "After Bonferroni correction (PMR-Wald < 6.82 × 10−6), we found that genetically proxied TNFRSF1A inhibition decreased white blood cell counts (total leucocytes, eosinophils, monocytes, basophils, and lymphocytes), decreased platelet count and was protective for Ankylosing spondylitis." (PMID 35768473, 2022).
autoinflammatory syndrome (10 papers, 2006 to 2023). A group of disorders of the innate immune system characterized by attacks of seemingly unprovoked inflammation without significant levels of either autoantibodies or autoreactive T cells more characteristic of autoimmune disease. "In a previous study, using a next generation sequencing approach, we found many rare variants and some functional polymorphisms in genes related to autoinflammatory syndromes (AID): CECR1, MEFV, MVK, NLRP3, NOD2, PSTPIP1 and TNFRSF1A in our BD cohort." (PMID 30808881, 2019). "IL-1β, IL-18, and IL-33 were within normal limits or undetectable, and no mutations were found in genes related to the pathogenesis of autoinflammatory syndromes (MEFV, MVK, TNFRSF1A, NLRP3, and NLRP12)." (PMID 34829952, 2021).
Hyperglycemia (10 papers, 2009 to 2025). An increased concentration of glucose in the blood. "To provide functional validation of TNFRSF1A dysregulation across species and confirm that its upregulation occurs in the context of hyperglycemia-induced kidney injury, we employed a zebrafish pdx1 knockdown model." (PMID 41516155, 2025). "Likewise, hyperglycemia in periodontal ligament stem cells showed impaired cellular functions and higher expression of TNFRSF1A (TNFR1)." (PMID 34922513, 2021).
asthma (8 papers, 2015 to 2023). "We discovered that the TNFRSF1A/1B-GRN signaling between MC3 and macrophages was significantly elevated in asthma, which suggests that MC3 may mediate the coordination of immune responses in the asthmatic model." (PMID 36439114, 2022).
ischemia (8 papers, 2010 to 2023). A hypoperfusion of the BLOOD through an organ or tissue caused by a PATHOLOGIC CONSTRICTION or obstruction of its BLOOD VESSELS, or an absence of BLOOD CIRCULATION. "Multiple microglia-related genes such as Cxcl10, Tlr7, Cd86, Tnfrsf1a, Nfkbia, Tgfb1, Ccl2 and Il-6, were upregulated with prolonged ischemia." (PMID 35154109, 2022).
lung adenocarcinoma (8 papers, 2010 to 2026). A carcinoma that arises from the lung and is characterized by the presence of malignant glandular epithelial cells. "This analysis showed that low expression of TNFRSF1A in LUAD (lung adenocarcinoma) was associated with significantly longer PFS and OS." (PMID 35899106, 2022).
ovarian carcinoma (8 papers, 2014 to 2025). A malignant neoplasm originating from the surface ovarian epithelium. "Furthermore, using a Human Apoptosis Array Kit consisting of 35 apoptosis-related proteins (R&D) with either miR-141-overexpressing or KLF12 knockdown ovarian cancer cells, 8 out of 35 proteins (HO-2/HMOX2, ph-Rad 17, CIAP-2, survivin, HSP-70, TNFR1/TNFRSF1A, clusterin and XIAP) were upregulated." (PMID 28095864, 2017).
epilepsy (7 papers, 2016 to 2025). A brain disorder characterized by episodes of abnormally increased neuronal discharge resulting in transient episodes of sensory or motor neurological dysfunction, or psychic dysfunction. "TNFRSF1B could be triggered as a survival mechanism to compensate for the extensive neuronal cell death found in epilepsy-associated HS or its expression could enable the harmful consequences of TNFRSF1A activation." (PMID 27006531, 2016). "This study identified 15 key genes linked to epilepsy, such as RPS6KA3 and TNFRSF1A, which are involved in lipid metabolism, apoptosis, and inflammation." (PMID 40520613, 2025). "Anti-inflammatory treatments targeting genes, including TNFRSF1A and IL7R, are essential for epilepsy patients exhibiting pronounced inflammatory responses." (PMID 40520613, 2025). "The nomogram, using RELA, PRKAB1, TNFRSF1A, CAMKK2, and CPT1B, was next confirmed as a reliable predictive model for epilepsy that would bring patients a net clinical benefit when the threshold probability ranged from 0.1 to 1.0." (PMID 36138892, 2022).
lymphoma (7 papers, 2010 to 2026). A malignant (clonal) proliferation of B- lymphocytes or T- lymphocytes which involves the lymph nodes, bone marrow and/or extranodal sites. "Subsequent experimental validation using small interfering RNA-mediated knockdown and coculture assays confirmed that disrupting the macrophage-intrinsic TNFRSF1A/NF-κB/BAFF axis eliminated the protective support provided by TAMs to lymphoma cells." (PMID 42231904, 2026).
pneumonia (7 papers, 2016 to 2025). An acute, acute and chronic, or chronic inflammation focally or diffusely affecting the lung parenchyma, caused by an infection in one or both of the lungs (by bacteria, viruses, fungi, or mycoplasma.). "The prioritisation of TNFRSF1A as a risk gene for pneumonia susceptibility was also notable given the existence of pre-clinical compounds developed for its inhibition in acute respiratory distress syndrome." (PMID 35768473, 2022). "We note that there was a trend (PMR-Wald < 1 × 10−4) towards a protective effect of TNFRSF1A inhibition on FinnGen pneumonia and infection phenotypes, along with evidence for an increased risk of cramps and vitamin B12 anaemia." (PMID 35768473, 2022). "The remaining three genes, PTGER4, TNFRSF1A, and LTBR displayed mixed directions of expression relative to the pneumonia risk increasing allele when annotating individual SNPs with eQTLs depending on the tissue considered." (PMID 35768473, 2022).
skin cancer (7 papers, 2010 to 2024). "Recent studies have demonstrated that TNFRSF1A-mediated signaling contributes to the promotion of tumor formation in various cancers, including liver cancer, skin cancer, gastric carcinogenesis, and esophageal squamous cell carcinoma (ESCC), as well as the facilitation of cancer cell metastasis." (PMID 38560169, 2024).
cryopyrin-associated periodic syndrome (6 papers, 2017 to 2024). Cryopyrin associated periodic syndrome (CAPS) defines a group of autoinflammatory diseases, characterized by recurrent episodes of systemic inflammatory attacks in the absence of infection or autoimmune disease. "The best known HRF are Familiar Mediterranean Fever (FMF), Cryopyrin-Associated Periodic Syndrome (CAPS), TNF-receptor associated periodic fever syndrome (TRAPS) and Mevalonate-Kinase Deficiency (MKD), caused by mutations in MEFV, NLRP3, TNFRSF1A and MVK genes, respectively." (PMID 29047407, 2017).
osteoporosis (6 papers, 2011 to 2025). A condition of reduced bone mass, with decreased cortical thickness and a decrease in the number and size of the trabeculae of cancellous bone (but normal chemical composition), resulting in increased fracture incidence. "In this study, we focused on investigating the interaction between SNPs in TNFα and its receptors (TNFRSF1A and TNFRSF1B), MAP infection, and active osteocalcin levels (an osteoporosis marker) in blood samples from RA patients." (PMID 31817071, 2019). "Here, we studied the frequency and effects of SNPs in TNFα/TNFRSF1A/TNFRSF1B in RA including gene expression, MAP infection, and osteoporosis marker levels in blood (54 RA and 48 healthy controls)." (PMID 31817071, 2019).
AIDS (5 papers, 2008 to 2025). A syndrome resulting from the acquired deficiency of cellular immunity caused by the human immunodeficiency virus (HIV). "TRAPS is the most variable entity among AIDs in terms of age of disease onset, frequency, duration, and severity of inflammatory flares, and this heterogeneity is probably linked to the wide spectrum of TNFRSF1A mutations." (PMID 26357457, 2015). "Multiple studies have indicated that somatic mutations in immune cells could contribute to AIDs, including CAPS (caused by NLRP3 variants) and TNF receptor-associated periodic syndrome (caused by TNFRSF1A variants)." (PMID 41168503, 2025).
head and neck cancer (5 papers, 2011 to 2022). A primary or metastatic malignant neoplasm affecting the head and neck. "This study aimed to assess the relationship between a functional polymorphism of the TNFRSF1A gene and the occurrence of nutritional disorders in patients subjected to radiotherapy due to head and neck cancer." (PMID 35884467, 2022).